OTX2 (orthodenticle homeobox 2)
Diseases named in the same sentence as OTX2 in open-access papers (continued):
Sharing a sentence is not in itself a finding about the gene and the disease.
small cell lung carcinoma (1 paper, 2024). Small cell lung cancer (SCLC) is a highly aggressive malignant neoplasm, accounting for 10-15% of lung cancer cases, characterized byrapid growth, and early metastasis. "In small cell lung carcinomas, OTX2 was also associated with MYC activity, though this was regulated by NEUROD1 and not ASCL143." (PMID 39349591, 2024).
T-cell lymphomas (1 paper, 2014). "Similarly the targeting of novel genes that were not seen in previous large-scale screens of MoMLV-induced T-cell lymphomas (e.g. Otx2, Myo16) is not merely due to their up-regulation in the background of the Runx2/MYC model." (PMID 24586197, 2014).
Wilms tumor (1 paper, 2020). An embryonal neoplasm characterized by the presence of epithelial, mesenchymal, and blastema components. "Other aberrations, such as the OTX2 amplification in the lymph node sample and the 11p deletion in the orbital metastasis (aberration mainly described in Wilms tumors in children), may be contributing to the phenotypes, although no clear association could be established." (PMID 32971811, 2020).
tumor (36 papers, 2010 to 2025). "In agreement, co-immunoprecipitation studies demonstrated the association of SOX2 and OTX2 in CP tumor cells." (PMID 40128799, 2025). "Through various analyses and experimental models, we unveil OTX2’s multifaceted influence, showing its association with heightened cell growth, increased migratory behaviors within the tumor microenvironment, and promotion of aggressive behavior in MB." (PMID 38674001, 2024). "As expected, MYC and OTX2, the two well-established oncogenic driver TFs of G3-MB, are revealed as subtype-specific SE-associated oncogenes of G3-MB tumor tissues." (PMID 36273157, 2022). "Homeoproteins orthodenticle OTX1 and OTX2 are neuronal transcription factors participating to adaptation during inflammation and underlying tumor growth both in the central nervous system and in the periphery." (PMID 32095330, 2020). "Our data reveal novel associations between OTX2 and axon guidance genes and underscore a potential tumor‐suppressive role for these neurodevelopmental cues in Group 3 and Group 4 tumors." (PMID 29377567, 2018). "Collectively, these results provide further evidence that SEMA genes are associated with a tumor‐suppressive role and contribute to the OTX2 KD phenotype in MB tumorspheres." (PMID 29377567, 2018). "Indeed, the enhanced glial progenitor-like profiles including Rspo1, Zfp423, and Msx1 were significantly reduced, whereas Otx2 mRNA levels remained unaltered in Sox2-deficient tumor cells." (PMID 40128799, 2025). "The results indicated that OTX2 deficiency enhanced tumor formation of HCT116." (PMID 35712778, 2022). "Moreover, although WNT signaling is activated by APC mutations in FAP neoplasms, reduced inactivation of OTX2 and activation of MYC may contribute to tumor development in FAP." (PMID 30220972, 2018). "Exploiting recent large data libraries, we analyzed the gene expression status of the OTX2 gene in two independent human MB datasets (N = 90) compared to that of normal cerebellum and found that the OTX2 gene is overexpressed in Group 3 MB tumor tissues." (PMID 38674001, 2024). "In silico analysis of human MB tumor samples reinforced the clinical relevance, revealing a robust positive correlation between OTX2 and mTOR mRNA expressions across diverse datasets." (PMID 38674001, 2024). "Analysis of human MB tumor samples (N = 952) revealed a positive correlation between OTX2 and mTOR mRNA expression, emphasizing the clinical significance of OTX2’s role in the mTORC2 pathway." (PMID 38674001, 2024). "Recognizing the pivotal role of the OTX2 gene as one of the major canonical driver genes of aggressive MB subgroup 3, we investigated the possible contributions of the OTX2 gene on MB tumor growth and LMD." (PMID 38674001, 2024). "To further explore the relevance of OTX2-regulated splicing, we expanded our findings to primary MB tumours." (PMID 39025928, 2024). "Analysis of human MB datasets revealed heightened OTX2 expression in these specific tumor subtypes, aligning with previous indications of OTX2’s regulatory involvement in these groups." (PMID 38674001, 2024). "The finding that OTX2 is overexpressed in Group 3 MB tumor tissues aligns with previous research indicating the involvement of OTX2 as a key regulatory gene in these specific subgroups of MB." (PMID 38674001, 2024). "An important role of altered SMARCA4 in MB development was suspected before since the overexpression of SMARCA4 wild-type represses tumor development in an OTX2/MYC Group 3 MB mouse model." (PMID 37919824, 2023). "As a result, an OTX2-SE-ARL4D regulatory axis is revealed to represent an important subtype-specific tumor dependency of G3-MB via contributing to maintaining cell cycle progression and repressing neural differentiation." (PMID 36273157, 2022). "It predicts novel transcription factors based on enhancer information, and experimentally proves OTX2 as a critical tumor suppressive transcription factor." (PMID 35712778, 2022).
tumor (continued). "Our study provides mechanistic insight into the networks controlled by OTX2 in MB stem/progenitor cells and reveals novel roles for axon guidance genes and their downstream effectors as putative tumor suppressors in MB." (PMID 29377567, 2018). "Only small nests of tumor cells were observed, if any, following injection of 5 × 104 D283 OTX2 KD cells." (PMID 29377567, 2018). "It will be of great benefit to study the regulatory pathways that control OTX2 expression in order to develop specific drugs to reduce OTX2 gene activity in tumours." (PMID 30100614, 2018). "We unravel an unexpected, mandatory function for Otx2 in sustaining cell proliferation and long-term maintenance of these tumours in vivo, therefore bringing unpredicted insight into the mechanisms of type 2 medulloblastoma subsistence." (PMID 30100614, 2018). "The majority of genes associated with axon guidance pathways were negatively correlated with OTX2 expression and self‐renewal suggesting a novel tumor‐suppressive role in these tumors." (PMID 29377567, 2018). "This was supported by a decrease in Ki67 staining for tumor cell proliferation in D283 OTX2 KD tumors." (PMID 29377567, 2018). "Here, we show that the transcription factor orthodenticle homeobox 2 (OTX2) promotes self‐renewal while inhibiting differentiation in vitro and increases tumor initiation from MB stem/progenitor cells in vivo." (PMID 29377567, 2018). "Taken together, these results demonstrate that OTX2 contributes to both tumor growth and tumor initiation from MB tumorspheres in vivo." (PMID 29377567, 2018). "A recent report suggested OTX2 as a probable therapeutic target, since it decreases the tumor size and growth in RB xenografts." (PMID 28861107, 2017). "OTX2 thus represents an attractive potential drug target in this tumor type; however, as a ligand-independent transcription factor, inhibiting its function with standard small molecule approaches is challenging." (PMID 25198066, 2014). "Notably, we identified lncMB3 target gene cluster in this pathway, whose misregulation elevates the retinal TF OTX2, an oncogenic driver in G3 MB that boosts cell proliferation, suppresses apoptosis, and contributes to tumour aggressiveness." (PMID 41198629, 2025). "Regrettably, the mechanisms behind the metastasis of MB remain largely unknown, and research recognizing the role of OTX2 in MB has mainly focused on the epigenetic and transcriptional activation of cell cycle genes and tumor growth." (PMID 38674001, 2024). "CERES score has been used to predict the potential roles of a gene in cancer, and we found that OTX2 might play a tumor suppressive role." (PMID 35712778, 2022). "As a oncogenic driver TF of G3-MB, OTX2 has been previously shown to promote tumor cell cycle progression via direct activation of multiple cell cycle genes and inhibit neural differentiation via repressing transcription of various neurodevelopmental genes directly or indirectly." (PMID 36273157, 2022). "From the predicted TF table, we also found that the score of Otx2 was high in tumor stages." (PMID 35712778, 2022). "Finally, we addressed the function of Otx2 in the context of type 2 medulloblastomas by directing Shh-dependent tumour formation in Otx2+ cells of the developing cerebellum and assessing the effects of Otx2 ablation in this context." (PMID 30100614, 2018). "In contrast, long-term follow-up of tumour development revealed striking effects of Otx2 ablation." (PMID 30100614, 2018). "In contrast, prolonged absence of Otx2 causes a totally different evolution, as specific regression of tumour development is observed in sKO animals, therefore unravelling an unexpected, mandatory function for Otx2 in sustaining long-term maintenance of type 2 medulloblastoma in vivo." (PMID 30100614, 2018).
tumor (continued). "To address this hypothesis, we have developed a novel tumour model of type 2 medulloblastoma by inducing constitutive Shh signalling in Otx2+ GCPs of the postnatal cerebellum and assessing the effect of Otx2 loss of function in this model." (PMID 30100614, 2018). "A minimal level of Otx2 could then become necessary to maintain tumour cell proliferation and block the mechanisms that normally allow GCPs to stop proliferating." (PMID 30100614, 2018). "Importantly, limiting dilution analysis comparing tumor growth from 2 × 105, 1 × 105, and 5 × 104 D283 scramble relative to D283 OTX2 KD tumorsphere cells revealed a decrease in tumor‐initiating capacity following OTX2 KD." (PMID 29377567, 2018). "The identification of functionally relevant, OTX2-regulated spliced variants of early (PPHLN1) and late (MADD) rhombic lip lineage genes adds complexity to this model, as we now demonstrate a definitive role for alternative splicing program alterations in MB tumour progression." (PMID 39025928, 2024). "Based on this, we hypothesize that a joint analysis of the different MB cell-types would better capture the local functional interactions of MYC and OTX2 across different tumor subtypes and would eventually help in delineating their global role in regulating metabolic processes in MB cells." (PMID 37016281, 2023). "In addition to its potential to contribute to tumor initiation, a role for Otx2 in cell migration could serve as a mechanism of tumor metastasis, consistent with the known association between OTX2 and tumor progression." (PMID 22558385, 2012). "Several genes previously reported as subgroup-specific drivers or tumor lineage markers, such as PTCH1, PDE1C, and ST18 in SHH and OTX2, EOMS, and LMX1A in G3, were recovered and detected as DEGs exclusively in GNP and RL, respectively." (PMID 41029754, 2025). "While Group 3 tumors mainly expressed photoreceptor markers, Group 4 tumor cells expressed mainly UBC markers, including EOMES, OTX2, NNAT, and LMX1A consistent with their proposed cells of origin." (PMID 39659836, 2024). "Moreover, through in-depth exploration and in silico analysis of human MB tumor samples, we found a positive correlation between OTX2 and mTOR mRNA expression in three independent MB datasets (N = 952), emphasizing the clinical significance of OTX2’s regulatory impact on the mTORC2 pathway." (PMID 38674001, 2024). "Group 3-MB exhibits orthodenticle homeobox 2 (OTX2) amplification, which upregulates MYC expression, thereby promoting tumor formation." (PMID 38391759, 2024). "Like GP3-C2, GP4-C2, the photoreceptor differentiated tumor cell cluster of G4-MB, exhibits the highest expression of ARL4D and highly expresses OTX2 and CRX." (PMID 36273157, 2022). "Using the information about the dynamic enhancer regions at different stages, we further predicted multiple TFs, and then identified Otx2 as one novel TF involved in CRC, which plays a tumor‐suppressive function." (PMID 35712778, 2022). "Parallel experiments with MB cells revealed that OTX2 exerts inhibitory effects on hEN and SHH MB cells by regulating growth, self-renewal and migration in vitro and tumor growth in vivo." (PMID 26398939, 2015). "Accordingly, transcript levels for seven of these genes were evaluated, with five of them (MEIS1, HOXA3, OTX2, TWIST1, and PROM1) being underexpressed in the tumor samples." (PMID 25908946, 2015). "Moreover, our scRNA-seq data analysis also revealed ARL4D, OTX2 and CRX were all enriched in GP3-C2, the photoreceptor differentiated tumor cell cluster of G3-MB defined in a recent single-cell transcriptomic study of MB." (PMID 36273157, 2022).
tumor (continued). "An OTX2-SE-ARL4D regulatory axis was further revealed to represent a subtype-specific tumor dependency and therapeutic target of G3-MB via contributing to maintaining cell cycle progression and inhibiting neural differentiation of tumor cells." (PMID 36273157, 2022). "Recent studies have also shown OTX2 is potentially required for tumor proliferation in the SHH group, although not necessarily for tumor formation." (PMID 35546872, 2022). "Extrapolation of this observation to human type 2 medulloblastomas would imply that deregulation of SHH signalling does not require more than normal OTX2 levels to ensure tumour cell proliferation." (PMID 30100614, 2018). "As hENs are normal cells not amenable to tumor formation and all cellular properties were reduced following OTX2 overexpression, we did not inject hENs and OTX2+ hENs into NOD SCID mice." (PMID 26398939, 2015). "Therefore, it would be interesting to test in future whether ARL4D also works as an essential gene and is transcriptionally regulated by OTX2 and CRX as well in ARL4D-high G4-MB tumors if proper tumor models are available." (PMID 36273157, 2022). "Moreover, the tumor cell subpopulations expressing the highest level of PSMB5 (GP3-B1) are different from the ones of MYC, OTX2 or CRX (GP3-B2 for MYC, GP3-C2 for OTX2 and CRX), further supporting the involvement of unidentified SE-associated TFs in regulating PSMB5 transcription in G3-MB." (PMID 36273157, 2022). "We did not detect any consistent changes in MYC and OTX2 expression upon modulation of the Activin pathway, suggesting that this signaling pathway does not regulate these two genes in Group 3 tumors and promotes tumor growth through other mechanisms." (PMID 31328883, 2019). "We demonstrate that although Otx2 ablation in this context does not prevent the formation of tumours, it strongly impairs their long-term maintenance, demonstrating for the first time, the critical role of this factor in regulating proliferation and tumorigenesis in the perinatal cerebellum." (PMID 30100614, 2018). "Together, these data indicate that, while Otx2 does not act as a driver of type 2 medulloblastoma tumoral transformation, as suggested before, it unexpectedly plays a mandatory function in sustaining these tumours over time." (PMID 30100614, 2018). "Following validations in vitro, 5.0×105 (trans-hEN OTX2 knockdown and trans-hEN scramble) and 2.5×105 (D283 OTX2 knockdown and D283 scramble) cells were injected into the right frontal lobe (n=5 for each condition and cell line) of NOD SCID mice and examined for tumor formation after 45 days." (PMID 26398939, 2015). "Simultaneous ablation of Otx2 in the Otx2CreERT2/flox;R26SmoM2/SmoM2 sKO line neither affected early GCP expansion and EGL hyperplasia at P11 and P15 nor the extent of tumoral development at P30, or tumour size before this stage (sup." (PMID 30100614, 2018). "Also, enhancement of OTX2 (orthodenticle homeobox 2) protein levels, involved in ATRA-mediated tumor cell death, has been shown in D283-Med but not in DAOY cells." (PMID 27317342, 2016).
cancer (16 papers, 2010 to 2025). A tumor composed of atypical neoplastic, often pleomorphic cells that invade other tissues. "We recently demonstrated that MB is a cancer of the developing human rhombic lip, with OTX2 maintaining rhombic lip identity and suppressing differentiation." (PMID 39025928, 2024). "Here we show that DZNep reduces Otx2/c-MYC cancer cells growth ex vivo highlighting a possible therapeutic function of EZH2 inhibition." (PMID 31996670, 2020). "Pioneer transcription factors (such as ASCL1 or OTX2) capable of reprogramming cancer cells may identify novel transcriptional and proteomic profiles that could be targeted to inhibit complete transdifferentiation into a pure small cell/neuroendocrine lineage state." (PMID 39349591, 2024). "OTX2 and other photoreceptor TFs, including NRL and CRX, drives anti-apoptotic factors like BCL2L1, linking this gene program to sustained cancer cell viability." (PMID 41198629, 2025). "During retinal development, OTX2 occupies a pivotal position in a photoreceptor gene hierarchy, including basic leucine zipper TFs NRL and CRX, both overexpressed in G3 MB, where they promote cancer survival via the anti-apoptotic factor BCL2L1." (PMID 41198629, 2025).
infection (5 papers, 2016 to 2024). The state of being infected such as from the introduction of a foreign agent such as serum, vaccine, antigenic substance or organism. "Eleven days after infection, the chromatin was crosslinked and immunoprecipitated with anti-OTX2 antibodies or negative control." (PMID 26985665, 2016). "The RDH10 promoter was amplified in cells transduced by AAV2.1-OTX2 when the OTX2 was used but not the anti-rabbit antibodies showing that OTX2 expressed through the use of AAV infection is binding to the RDH10 promoter." (PMID 26985665, 2016). "It is not through homodimerization with OTX2 since the interaction does not require the co-infection of OTX2S with OTX2." (PMID 26985665, 2016).
neurological disorders (2 papers, 2020 to 2021). "PIGY upstream reading frame and orthodenticle homeobox 2 are genes associated with MIA-related neurological disorders, and presented significant under-expression in weaned relative to nursed pigs exposed to MIA, with a moderate pattern observed in non-MIA pigs." (PMID 33856433, 2021). "Hypermethylated genes involved in neurological disorders include AGAP1, CACNA1A, and OTX2." (PMID 32850550, 2020).
neurodegenerative disease (1 paper, 2016). A disorder of the central nervous system characterized by gradual and progressive loss of neural tissue and neurologic function. "Considering Otx2 function in maintaining the mature structure of PNNs in the adult, blocking Otx2 transfer could be used to promote cognitive flexibility and enhance memory acquisition in neurodegenerative diseases, for instance." (PMID 26881132, 2016).
neurodevelopmental disorder (1 paper, 2024). A behavioral and cognitive disorder with onset during the developmental period that involves impaired or aberrant development of intellectual, motor, or social functions. "In summary, our study provides new insights into the molecular mechanisms of anterior patterning of the neuroectoderm by cooperation with Zbtb11 and phosphorylated form of Otx2 as well as the neurodevelopmental disorders caused by dysregulation of Zbtb11." (PMID 39083515, 2024). "Our study showing the interactions between Zbtb11 and Otx2 might provide a basis for the therapeutic potential of Zbtb11 in neurodevelopmental disorders associated with mitochondrial dysfunction, as well as for elucidating the molecular mechanisms of early anterior neural development." (PMID 39083515, 2024).
psychiatric disorder (1 paper, 2021). A disorder characterized by behavioral and/or psychological abnormalities, often accompanied by physical symptoms. "Manipulating OTX2 levels in the ChP and CSF, coupled with behavioral therapies, may hold promising opportunities for psychiatric disorders." (PMID 33963285, 2021).